OPTN (optineurin)
Diseases named in the same sentence as OPTN in open-access papers (continued):
Sharing a sentence is not in itself a finding about the gene and the disease.
Salmonella Infections (4 papers, 2018 to 2025). Infections with bacteria of the genus SALMONELLA. "In line with this, OPTN-deficient HeLa cells exhibited a bacterial handling defect after Salmonella infection similar to a more severe phenotype after Salmonella infection in mice that was independent from NF-κB or type I IFN responses in macrophages." (PMID 29692785, 2018). "As an autophagy receptor, OPTN controls the clearance of Salmonella infection and mediates mitochondrial turnover." (PMID 29692785, 2018). "This was first revealed for the receptor protein optineurin (OPTN) that becomes phosphorylated by the kinase TANK-binding kinase 1 (TBK1) in response to cellular Salmonella infection and it was shown that preventing this phosphorylation reduced the efficiency of LC3 targeting to invading bacteria." (PMID 31450711, 2019). "Interestingly, some bacterial and viral KEGG pathways, such as “Salmonella infection” and “HTLV-I infection,” were selectively enriched in the upregulated gene set, underscoring a complex and non-uniform transcriptional landscape in optineurin-deficient cells." (PMID 41226491, 2025).
breast carcinoma (3 papers, 2017 to 2025). "For example, in breast cancer (BRCA) we found that OPTN, PINK1 and PRKN expression was positively correlated with infiltration of NK cells, while that of BECN1 was negatively correlated with it." (PMID 39859167, 2025). "Compared with the normal mammary tissues, breast cancer tissues showed an obvious reduction in BECN1, ATG16L1 and SQSTM1 levels, whereas OPTN expression was higher in cancer tissues." (PMID 28628113, 2017).
cognitive decline (3 papers, 2019 to 2021). "OPTN-deficient mice challenged with HSV-1 show significant cognitive decline and susceptibility to lethal CNS infection." (PMID 34518549, 2021). "Based on these observations, we speculate that inhibition of autophagy flow may be involved in OPTN‐related cognitive decline, though the detailed mechanisms need further investigation." (PMID 34528736, 2021). "We show that mice lacking OPTN demonstrate accelerated decline in cognitive functions following HSV-1 infection, underscoring the role of OPTN and HSV-1 in the potential etiology of neurodegeneration with cognitive decline." (PMID 34518549, 2021). "Combination of the elevated platelet optineurin and rGSK‐3β(T/S9) enhanced the MCI‐discriminating efficiency with AUC of 0.927, specificity of 86.7%, sensitivity of 85.3%, and accuracy of 0.859, which is promising for predicting cognitive decline in T2DM patients." (PMID 34528736, 2021).
diabetic retinopathy (3 papers, 2020 to 2022). "Furthermore, the mitophagy markers LC3 and OPTN are also higher in the retinal microvasculature from donors with diabetic retinopathy." (PMID 31938715, 2020).
glioblastoma (3 papers, 2022 to 2025). The most malignant astrocytic tumor (WHO grade IV). "Consistently, Western blot analysis confirmed that SL reduced OPTN protein level in a time‐ and concentration‐dependent manner in glioblastoma cell lines GBM‐3, LN‐229, and T98G." (PMID 40990506, 2025). "Moreover, the first evidence that SL upregulates TRIM16 expression is presented, which acts as an E3 ubiquitin ligase for OPTN degradation in glioblastoma." (PMID 40990506, 2025). "All methods consistently confirmed the interaction between TRIM16 and OPTN in glioblastoma cells." (PMID 40990506, 2025). "Furthermore, flow cytometry analysis revealed that OPTN overexpression significantly reduced SL‐induced apoptosis in glioblastoma cells." (PMID 40990506, 2025). "We hypothesized that OPTN plays a crucial role in the SL‐induced autophagy inhibition and apoptosis induction in glioblastoma cells." (PMID 40990506, 2025). "However, another study revealed an opposing effect of mitophagy on cancer cells, as the platelet-derived growth factor (PDGF)-METTL3 axis could downregulate the expression of optineurin (OPTN), inhibiting mitophagy and promoting cancer stem cell maintenance in glioblastoma." (PMID 41373022, 2025). "Sanggenol L, a flavonoid from mulberry, enhances glioblastoma sensitivity to temozolomide by inhibiting mitophagy and inducing apoptosis through TRIM16‐mediated OPTN degradation." (PMID 40990506, 2025).
inflammatory bowel disease (3 papers, 2018 to 2025). A spectrum of small and large bowel inflammatory diseases of unknown etiology. "Indeed, OPTN has been implicated in inflammatory bowel disease and both p62 and OPTN are involved in regulation of inflammatory signaling downstream of NF-κB." (PMID 30818338, 2019).
acute kidney injury (2 papers, 2022 to 2023). Sudden and sustained deterioration of the kidney function characterized by decreased glomerular filtration rate, increased serum creatinine or oliguria. "A recent study reported that PINK1-PARK2- optineurin-mediated mitochondrial autophagy is activated and plays a protective role in septic acute kidney injury." (PMID 38099142, 2023). "The PINK1/PARK2/OPTN (optineurin) pathway of mitophagy is activated for protection in septic acute kidney injury." (PMID 36187470, 2022).
Autoimmunity (2 papers, 2018 to 2021). The occurrence of an immune reaction against the organism's own cells or tissues. "In aggregate, these results suggest that SSD ameliorates experimental autoimmunity through OPTN modulation." (PMID 34707127, 2021). "We next employed a classical central nervous system (CNS) autoimmunity animal model EAE to explore the role of OPTN in regulating inflammatory injuries in vivo." (PMID 34707127, 2021). "Our findings thus highlight a pivotal function of OPTN for the regulation of DC functions and autoimmune disorders." (PMID 34707127, 2021). "Whether H486R mutation in OPTN causes autoimmunity or not, is not known." (PMID 29951055, 2018). "Furthermore, we found that SSD specifically depends on OPTN to modulate DC maturation and EAE progression, potentially representing an OPTN targeting drug for autoimmune disorders." (PMID 34707127, 2021).
cervical cancer (2 papers, 2022 to 2024). A primary or metastatic malignant neoplasm involving the cervix. "Notably, NDP52 and OPTN, besides TAX1BP1, are the major receptors mediating PINK1-mediated mitophagy in human cervical cancer cell line (HeLa)." (PMID 35305662, 2022).
congenital glaucoma (2 papers, 2022 to 2024). "This hypothesis is supported by some forms of congenital glaucoma associated to optineurin mutations that interfere with mitophagy and autophagy." (PMID 36361544, 2022).
diabetic nephropathy (2 papers, 2018 to 2022). "Therefore, OPTN-mediated mitophagy plays a crucial regulatory role in high glucose-induced inflammation and renal tubular senescence in diabetic nephropathy." (PMID 36353377, 2022). "Of note, overexpression of OPTN significantly enhanced the activation of mitophagy by inhibiting NLRP3 inflammasome, retarded cell senescence and alleviated diabetic nephropathy, while OPTN silencing markedly inhibited high glucose-induced mitophagy." (PMID 36353377, 2022).
encephalitis (2 papers, 2021 to 2023). An acute inflammatory process affecting the brain parenchyma. "We have shown that acute CNS necroptosis can occur during HSV-1 infection in Optn−/− mice, leading to encephalitis, long-term neurodegeneration, and death, further supporting the anti-viral restriction by OPTN." (PMID 34518549, 2021).
Hyperglycemia (2 papers, 2017 to 2022). An increased concentration of glucose in the blood. "In this study, we suggest that OPTN K108su, caused by hyperglycemia-induced succinate accumulation, disrupts autophagic flux in RGCs, thus resulting in the accumulation of oxidatively damaged proteins or organelles in the cytoplasm, which might mechanistically underlie RGCs damage." (PMID 35165261, 2022). "(iii) The association of Parkin, E3 ubiquitin ligase, is also increased in MT under HG conditions, suggesting mitochondrial membrane protein ubiquitination and recognition by adapter proteins, such as OPTN and p62/SQSTM1, under sustained hyperglycemia." (PMID 28492550, 2017).
lysosomal storage disease (2 papers, 2022 to 2024). A metabolic disorder caused by mutations in proteins critical for lysosomal function, including lysosomal enzymes, lysosomal integral membrane proteins, and proteins involved in the post-translational modification and trafficking of lysosomal proteins. "Lysosomes hold potential as an attractive target for therapeutic intervention in ALS, as in addition to VCP, several other ALS associated genes have a role in lysosomal homeostasis (C9orf72, TARDBP, TMEM106B, TBK1, OPTN, SQSTM1) and several lysosomal storage diseases manifest neurological features." (PMID 39593143, 2024). "Similarly to OPTN and SQSTM1, also VCP and PFN1 share common roles in autophagic degradation raising the hypothesis of a common pathogenic mechanism affecting the formation and clearance of misfolded proteins in PDB, ALS and, more generally, in lysosomal storage diseases." (PMID 36035996, 2022).
muscular disease (2 papers, 2022 to 2023). Myopathy is a peripheral nervous system disease consisting of any abnormal condition or disease of the muscular tissues; commonly designates a disorder involving skeletal muscle. "Thus, OPTN may be a potential therapeutic target for the prevention and treatment of impaired myogenesis in injury and other muscular disease, such as DMD and aging." (PMID 35476671, 2022). "This review aims to summarize what has been studied so far about the direct involvement of aggrephagy and the activation of the key players, among others, p62, NBR1, Alfy, Tollip, Optineurin, TAX1BP1 and CCT2 in muscular diseases." (PMID 37176163, 2023).
ocular hypertension (2 papers, 2007 to 2015). Abnormally high intraocular pressure. "Analogous to wild-type and E50K optineurin transduced eyes, an enhanced optineurin, reduced PSMB5 and increased LC3 staining was observed in the RGC layer of sections from injury grades 2.75 and 5 compared to injury grade 1.0 (normal) in the rat ocular hypertension model." (PMID 25943884, 2015).
ocular melanoma (2 papers, 2022 to 2023). A melanoma that arises from the structures of the eye or ocular adnexa. "Metformin also inhibits the progression of ocular melanoma by inhibiting autophagy through histone deacetylation of optineurin (OPTN), a key candidate for autophagosome formation and maturation." (PMID 37344841, 2023). "As OPTN was significantly upregulated in tumours and modulated autophagic flux in ocular melanoma, we explored the role of OPTN in the tumour progression of ocular melanoma." (PMID 35075807, 2022). "Overall, we revealed for the first time that metformin significantly inhibited the progression of ocular melanoma, and verified that metformin acted as an autophagy inhibitor through histone deacetylation of OPTN." (PMID 35075807, 2022). "To further verify the relationship between metformin‐guided autophagy inhibition and OPTN expression, we rescued OPTN expression after metformin treatment in ocular melanoma cells by overexpressing OPTN (PBS/OPTN group)." (PMID 35075807, 2022). "The results demonstrated that the histone acetylation level was significantly upregulated in ocular melanoma cells, which is in accordance with the specific OPTN upregulation in ocular melanomas." (PMID 35075807, 2022). "Here, we revealed for the first time that OPTN acts as an oncogene in ocular melanomas in which it is specifically highly expressed, and is associated with unfavourable outcomes in tumour patients." (PMID 35075807, 2022). "Intriguingly, we found that metformin significantly attenuated autophagic flux in ocular melanoma cells by epigenetically silencing optineurin (OPTN)." (PMID 35075807, 2022). "Furthermore, through a cohort of 81 ocular melanoma patients, we found that OPTN was significantly upregulated in ocular melanoma samples compared to normal nevus tissue samples." (PMID 35075807, 2022). "Taken together, our data show that OPTN is a key autophagic regulator in ocular melanoma cells and may serve as a downstream factor of metformin." (PMID 35075807, 2022). "Similarly, we further observed a significant increase in the histone acetylation level of OPTN promoter in metformin‐treated ocular melanoma cells through the chromatin immunoprecipitation (ChIP) assay." (PMID 35075807, 2022). "In addition, we demonstrated that metformin acts as an autophagy inhibitor through histone deacetylation of OPTN, which serves as a novel oncogene in ocular melanoma." (PMID 35075807, 2022). "Taken together, these results showed that OPTN was an oncogene in ocular melanoma." (PMID 35075807, 2022). "Moreover, we found that after metformin treatment, the histone acetylation level of the OPTN promoter was significantly downregulated in ocular melanoma cells (lanes 5 and 6)." (PMID 35075807, 2022). "Furthermore, we verified the function of OPTN in ocular melanoma in vivo through an intraocular xenograft tumour model combined with luciferase animal imaging." (PMID 35075807, 2022). "In addition, we observed that OPTN was significantly upregulated in ocular melanoma cells at both RNA and protein levels." (PMID 35075807, 2022). "However, how OPTN functions in the tumourigenesis of ocular melanoma is to be fully addressed." (PMID 35075807, 2022). "More importantly, the H3K9Ac level in OPTN promoter was decreased after metformin treatment (lanes 9 and 10); however, H3K9Ac level largely restored after siSIRT1 (lane 12) and EX527 treatment (lane 12) in ocular melanoma cells." (PMID 35075807, 2022).
osteoporosis (2 papers, 2021 to 2023). A condition of reduced bone mass, with decreased cortical thickness and a decrease in the number and size of the trabeculae of cancellous bone (but normal chemical composition), resulting in increased fracture incidence. "Cellular senescence also leads to a decrease in Optineurin (OPTN), an autophagy receptor therefore contributing to osteoporosis alongside with accumulation of the OPTN substrate fatty acid binding protein 3 (FABP3)." (PMID 34447754, 2021). "For instance, OPTN dysfunction regulates bone lipid homeostasis in the bone marrow cavity via the substrate fatty acid binding protein 3 (FABP3), leading to the onset of senile osteoporosis, and OPTN mutations maybe result in lipid metabolism abnormalities in patients and models of ALS." (PMID 38178841, 2023).
pancreatic cancer (2 papers, 2019 to 2021). "Remarkably, pancreatic cancer was associated with the second highest OPTN expression of all tumor tissues, superseded only by renal cancer, as shown in Fig. 2a36." (PMID 31428460, 2019). "Target specific siRNA (12.5 nM) knocked down OPTN expression successfully in three pancreatic cancer cell lines (Miapaca, Suit2-007 and BXPC3)." (PMID 31428460, 2019). "In this first study on the role of OPTN in experimental pancreatic cancer, it was tempting to reduce OPTN levels, which are generally increased in PDAC, by a knockdown strategy in order to investigate its value as therapeutic target." (PMID 31428460, 2019). "Based on publically available data we found that OPTN is highly expressed in cohort studies of 17 cancer types, with the highest expression in renal followed by pancreatic cancer, and the lowest expression detected in prostate cancer." (PMID 31428460, 2019). "The autophagy receptor OPTN is highly expressed in many human cancers including pancreatic cancer." (PMID 31428460, 2019). "Apoptosis was found to be upregulated in all cell lines in response to OPTN knockdown as proven by increased cleaved PARP expression, fragmentation of the nuclei by DAPI staining and increased Annexin V binding in respective pancreatic cancer cells." (PMID 31428460, 2019).
primary progressive aphasia (2 papers, 2021 to 2022). Primary progressive aphasia (PPA) is a neurodegenerative disorder, characterized by a primary dissolution of language, with relative sparing of other mental faculties for at least the first 2 years of illness. "We identified a novel OPTN variant (p.Gln79Arg), predicted to be pathogenic in silico, in a male patient with progressive primary aphasia, starting at 62 years old (patient 5)." (PMID 35873773, 2022).
retinal degeneration (2 papers, 2021). Degeneration of the retina. "Our study elucidated that the OPTN E50K mutation was associated with aggravation of age-related deficiency of NFs in both retinas and bone marrow, which may have led to retinal degeneration and reduced regenerative function in BM during NTG development." (PMID 34127652, 2021). "We found that the OPTN E50K mutation aggravated age-related deficiency of neurotrophic factors in both retinas and BM during NTG development, leading to retinal degeneration and BM dysfunction." (PMID 34127652, 2021).
Adult onset (1 paper, 2023). Onset of disease manifestations in adulthood, defined here as at the age of 16 years or later. "Furthermore, a study performed on 54 families with autosomal dominantly inherited adult-onset POAG led to the identification of sequence alterations in the gene OPTN of optineurin, expressed in trabecular meshwork, nonpigmented ciliary epithelium, retina, and brain." (PMID 37833756, 2023).
amyloidosis (1 paper, 2021). A disorder characterized by the localized or diffuse accumulation of amyloid protein in various anatomic sites. "Specifically, the proteins involved in amyloidosis, including optineurin (OPTN), ras‐related protein Rab‐21 (Rab21), dynamin 1 (DNM1), peroxisomal bifunctional enzyme (EHHADH), fermitin family homolog 2 (FERMT2), E3 ubiquitin‐protein ligase UBR1 were increased in T2DM‐MCI compared with T2DM‐nMCI." (PMID 34528736, 2021). "The MMSE‐correlated DEPs were mainly involved in amyloidosis (DNM1, UBR1, OPTN, FERMT2), CNS disorder (WIPF1) and energy metabolism (COA6, COX7C, PDPR) processes." (PMID 34528736, 2021).
autoimmune disorders (1 paper, 2021). "Together with the fact that pharmacological inhibition of OPTN by SSD can also prevent the progression of the experimental autoimmune disease, EAE, we highlight potentially promising DCs based immunotherapy for the treatment of autoimmune disease." (PMID 34707127, 2021). "Moreover, the natural product, Saikosaponin D (SSD), attenuates EAE symptom by inhibiting OPTN expression, suggesting that interfering OPTN could be beneficial for the therapeutic treatment of autoimmune diseases." (PMID 34707127, 2021).
Cerebral atrophy (1 paper, 2016). Atrophy (wasting, decrease in size of cells or tissue) affecting the cerebrum. "Neuroradiologically, a progressive cerebral atrophy has been shown in siblings with ALS who carried a mutation in the gene for optineurin (OPTN)." (PMID 27716404, 2016).
demyelinating disorders (1 paper, 2025). "Collectively, these data suggested that the intricate link between MLKL and OPTN that serves to maintain myelin, with dysregulation of this balance resulting in severe impairments in motor functions and behaviours reported typically in MS and MS‐like demyelinating disorders." (PMID 40490945, 2025).
disc degeneration (1 paper, 2022). "Our study highlights the mechanism by which OPTN mitigates disc degeneration and explores the potential of OPTN as a therapeutic target for IVDD." (PMID 36105191, 2022). "The expression level of OPTN decreased as disc degeneration increased in both human and rat NP specimens." (PMID 36105191, 2022). "Based on the results of the in vitro experiments, we then investigated the role of OPTN in vivo and established a rat model of needle puncture-induced disc degeneration." (PMID 36105191, 2022). "In conclusion, our findings suggest that enhancing mitophagy by targeting OPTN may be a potential strategy for treating disc degeneration." (PMID 36105191, 2022).
ganglion (1 paper, 2016). "Nevertheless, the role played by an OPTN E50K mutation in the pathogenic mitochondrial mechanism that underlies retinal ganglion cell (RGC) degeneration in POAG remains unknown." (PMID 27654856, 2016).